SIRT1 (sirtuin 1)
Diseases named in the same sentence as SIRT1 in open-access papers (continued):
Sharing a sentence is not in itself a finding about the gene and the disease.
demyelinating disease (7 papers, 2014 to 2025). A broad group of disorders that affect the myelin sheaths that cover the neurons. "SIRT1 activating compounds prevent neuronal loss in viral-induced demyelinating disease involves increasing mitochondrial biogenesis with reduction of oxidative stress." (PMID 34887866, 2021). "Results demonstrate that SIRT1 activating compounds prevent neuronal loss in viral-induced demyelinating disease similar to their effects in autoimmune-mediated disease." (PMID 24383546, 2014). "The current studies characterize mechanisms of neuronal loss in viral-induced demyelinating disease, and examine the ability of SIRT1 activating compounds to prevent neuronal loss, reduce oxidative stress, and regulate proteins that promote mitochondrial function." (PMID 24383546, 2014). "SIRT1 activating compounds represent potential new neuroprotective agents for demyelinating diseases." (PMID 24383546, 2014). "Together, results suggest SIRT1 promotes neuronal survival and prevents demyelination in CNS demyelinating diseases." (PMID 24383546, 2014). "Indeed, alteration of this protein in lesion sites of MS patients implies a potential role of SIRT1 modulation in demyelinating diseases that needs more clarification." (PMID 37131098, 2023). "Compounds that activate the NAD+-dependent SIRT1 deacetylase prevent neuronal loss in an autoimmune-mediated MS model, but the mechanism of this effect is unknown, and it is unclear whether SIRT1 activating compounds exert similar effects in demyelinating disease induced by other etiologies." (PMID 24383546, 2014). "New and innovative avenues for the investigation and treatment of demyelinating disorders are required that involve autophagy, apoptosis, FoxOs, mTOR, AMPK, SIRT1, and related systems with the APOE-ε4 gene and SARS-CoV-2." (PMID 37508898, 2023). "Taken together, these studies suggest that inactivation of SIRT1 may promote OLG differentiation and thus may be a target for improving symptoms of demyelinating diseases; on the other hand, increased SIRT1 expression in other brain cells during EAE may be anti-inflammatory and neuroprotective." (PMID 32328069, 2020).
Encephalopathy (7 papers, 2019 to 2025). Encephalopathy is a term that means brain disease, damage, or malfunction. "In fact, SIRT1 activation by Resveratrol prevented NLRP3 expression and IL-1β cleavage in hippocampus of mice with sepsis-associated encephalopathy." (PMID 31327964, 2019).
fluorosis (7 papers, 2016 to 2025). "We demonstrated that ASP could regulate the brain damage caused by fluorosis through the SIRT1/BDNF/TrkB signaling pathway, and reported the possible part played by ASP in preventing and treating fluorosis." (PMID 39041630, 2025). "The role of SIRT1 in selecting between cell survival and death provides a potential therapeutic strategy in fluorosis." (PMID 27564107, 2016). "SIRT1 is promising as a potential therapeutic target for dental fluorosis." (PMID 36060706, 2022). "Even though it has not been reported if 4PBA can affect SIRT1 (class III HDAC), it seems prudent to assess the effect of 4PBA on SIRT1 function in dental fluorosis." (PMID 28553235, 2017). "The application of antioxidants alone to reduce ROS instead attenuated the SIRT1/autophagic response and failed to reduce fluoride toxicity, suggesting that activation of JNK/SIRT1 signaling may be an important potential strategy to manage dental fluorosis." (PMID 36060706, 2022).
glucose metabolism disorders (7 papers, 2019 to 2025). "Studies have shown that catalpol ameliorates triptolide-induced hepatic glucose metabolism disorders and oxidative stress through the modulation of the Sirtuin 1 (SIRT1)/Hypoxia-Inducible Factor-1α (HIF-1α) signaling pathway." (PMID 41306276, 2025). "Our findings demonstrated that CAT treatment improved TP-induced hepatic glucose metabolism disorder and oxidative stress by modulating the SIRT1/HIF-1α pathway." (PMID 39113710, 2024). "Jing Fang granules have been found to improve autophagic flux by modulating LKB1/AMPK/SIRT1, thereby alleviating glucose metabolism disorders and inflammatory responses in mice with CSU." (PMID 38035098, 2023). "SIRT1 and SIRT3 are key melatonin targets; in rats, melatonin efficiently alleviates glucose metabolism disorders by decreasing mitochondrial dysfunction through activating SIRT1 and SIRT3." (PMID 36815979, 2023). "As per several studies, QC has actions on SIRT1, and in an investigation, the beneficial action of QC on lipid and glucose metabolism disorder were connected to the upregulation of SIRT1 expression and its impact on the Akt signaling pathway." (PMID 31717708, 2019).
head and neck squamous cell carcinoma (7 papers, 2014 to 2021). A squamous cell carcinoma that arises from any of the following anatomic sites: lip and oral cavity, nasal cavity, paranasal sinuses, pharynx, larynx, and salivary glands. "In this study, we focused on cell death in association with Sirt6/Sirt1 and reactive oxygen species (ROS) in head and neck squamous cell carcinomas (HNSCCs)." (PMID 33727672, 2021). "The SIRT1 expression is significantly downregulated in human head and neck squamous cell carcinoma (HNSCC)." (PMID 26318035, 2015). "In fact, we previously reported that head and neck squamous cell carcinoma (HNSCC) patients who exhibited SIRT1 expression often experienced tumor regression and had a favorable prognosis." (PMID 25146318, 2014).
Hyperinsulinemia (7 papers, 2013 to 2024). An increased concentration of insulin in the blood. "Long-term OZ treatment induced hypergastrin- and hyperinsulinemia and increased expression of Sirt1, Pparg, and Cxcl5 in mouse pancreatic tissues accompanied by specific changes in glucose metabolism." (PMID 38884019, 2024). "In conclusion, long-term OZ treatment induced hypergastrin- and hyperinsulinemia increased expression of Sirt1, Pparg, and Cxcl5 mRNA accompanied by specific changes in glucose metabolism." (PMID 38884019, 2024). "SIRT1 improves glucose tolerance, reduced hyperinsulinemia, and enhanced systemic insulin sensitivity and Sirt1 controls specifically the inflammatory status of macrophages and T lymphocytes regulating the metabolism and that of adipose tissues in obese mice." (PMID 30881341, 2019). "We also examined the regulation of tissue SIRT1 expression by hyperinsulinemia and circulating free fatty acids (FFA) elevation." (PMID 29417372, 2018). "The change in SIRT1 after hyperinsulinemia (ΔSIRT1) differed between normal-weight and obese subjects (p = 0.021)." (PMID 29417372, 2018). "In contrast, muscle SIRT1 expression increased after hyperinsulinemia (p = 0.016) in the entire study group." (PMID 29417372, 2018). "Since activation of SIRT1 can lead to improved glucose tolerance and insulin sensitivity it is speculated that SIRT1/NF-kB/JNK axis could play an important role in regulating hyperinsulinemia and hyperglycemic in inflamed hepatocytes." (PMID 34034759, 2021). "Hyperinsulinemia decreased SIRT1 expression in AT by approx. 20% (p = 0.046)." (PMID 29417372, 2018). "We aimed to assess adipose tissue and skeletal muscle sirtuin 1 expression in relation to insulin sensitivity, the expression of proinflammatory and metabolic genes, and to study the regulation of sirtuin 1 expression by hyperinsulinemia and circulating free fatty acids elevation." (PMID 29417372, 2018). "Furthermore, we observed that 6 h hyperinsulinemia decreased AT and increased skeletal muscle SIRT1 expression and that both effects were negated by concurrent Intralipid/heparin infusion." (PMID 29417372, 2018). "In addition, hyperinsulinemia increases SIRT1 expression in muscle tissue." (PMID 33806509, 2021). "Therefore, we can hypothesize that an increased muscle SIRT1 expression during hyperinsulinemia might represent an additional mechanism to maintain muscle glucose uptake." (PMID 29417372, 2018). "We next examined the effect of hyperinsulinemia and circulating FFA elevation on tissue SIRT1 expression." (PMID 29417372, 2018). "Also, we for the first time report the relationship between AT SIRT1 and SLC2A4 as well as the tissue-specific effect of hyperinsulinemia on SIRT1 expression." (PMID 29417372, 2018).
insulinoma (7 papers, 2015 to 2025). "Because of specificity issues, we generated an insulinoma cell line deficient in SIRT1 to further evaluate the role of this sirtuin in regulating Gadd45α expression in response to nitric oxide." (PMID 40147772, 2025). "In order to study the mechanisms by which SIRT1 regulates insulin secretion, two different immortalized insulinoma cell lines (rat INS-1 and murine MIN6) were silenced for SIRT1." (PMID 31557786, 2019). "Specifically, both mice SIRT1βKO islets and the murine insulinoma cell line (MIN6) knocked down for SIRT1 showed impaired glucose-stimulated insulin secretion (GSIS)." (PMID 31557786, 2019). "The results of an in vitro trial suggested that Sirt1/FoxO1 may be one of the potential therapeutic targets for LPS‐induced oxidative stress injury in rat insulinoma cells." (PMID 35959265, 2022). "It was reported that SIRT1 regulates forkhead box O1 (FoxO1) translocation, thereby directing an anti-apoptotic transcriptional program that protects INS 832/13 cells (a rat insulinoma cell line) from nitric oxide-induced apoptosis." (PMID 35538036, 2022). "Of note, our study uses a pancreas-specific Sirt1 deficiency and isolated islets thereof, which provides a more physiological model than the insulinoma-derived MIN6 cell line and which eliminates effects from Sirt1 deletion outside the pancreas." (PMID 26046931, 2015). "Consistent with that hypothesis, we now show that nitric oxide stimulates the expression of Gadd45α in insulinoma cells lacking SIRT1." (PMID 40147772, 2025).
intestinal tumor (7 papers, 2008 to 2025). "A recent report demonstrated that enhanced SIRT1 expression inhibited intestinal tumor formation in a β-catenin-dependent mouse model." (PMID 27528025, 2016). "Taken together, these observations show that SIRT1 suppresses intestinal tumor formation in vivo and raise the prospect that therapies targeting SIRT1 may be of clinical use in β−catenin-driven malignancies." (PMID 18414679, 2008). "In intestinal tumors, TNF-α disrupts interactions between IDH1 and the deacetylase SIRT1, leading to decreased IDH1 protein stability." (PMID 40906076, 2025).
mood disorder (7 papers, 2015 to 2025). A cognitive disorder a disturbance in which the person's mood is hypothesized to be the main underlying feature. "Furthermore, SIRT1 is recently implicated in the mood disorders of mice as well as humans, whereby the reduction in levels of SIRT1 in blood has been linked to the depressive behaviors." (PMID 31431514, 2019). "Recent studies have implicated SIRT1 in mood disorders in humans." (PMID 30271963, 2018). "Aside from mediating the neuroinflammatory pathways, as well as the Sirt1/NF-κB pathway, Isorhamnetin was shown to have antioxidant properties that are useful in counterbalancing oxidative stress, a recurrent hallmark of neurodegenerative diseases and mood disorders." (PMID 41317200, 2025). "NAD+ and SIRT-1 directly activate ATP production and upregulate circadian genes, suggesting a pathway of influence in mood disorders." (PMID 34295268, 2021). "Our findings support and provide more details for the theory that SIRT1 links energy metabolism and mood disorder regulation." (PMID 30271963, 2018).
overnutrition (7 papers, 2017 to 2025). An imbalanced nutritional status resulting from excessive intake of nutrients. "We demonstrate that maternal overnutrition is associated with increased lipid deposition and the suppression of multiple stress responses including autophagy, antioxidant defence and inflammation in the offspring kidney with a significant relevance to the SIRT1 signalling network." (PMID 28827681, 2017). "In fact, overnutrition is followed by an increase in mTORC1 levels, which leads to decreased SIRT1 and AMPK levels, resulting in autophagy inhibition." (PMID 41228388, 2025). "At least three signaling pathways are involved in SGLT2 inhibitor’s effect on autophagy flux in overnutrition diseases: mammalian target of rapamycin (mTOR), sirtuin 1 (SIRT1), and hypoxia-inducible factors (HIFs) pathways." (PMID 34744742, 2021). "Overnutrition, temperature dysregulation, and stress repress the heat shock gene Sirtuin 1 with the induction of HSP regulated amyloid beta aggregation involved in the autoimmune response." (PMID 29783682, 2018). "Thus, SGLT2 inhibitor upregulates SIRT1 and enhances autophagy flux in overnutrition diseases." (PMID 34744742, 2021).
pancreatic ductal adenocarcinoma (7 papers, 2013 to 2022). An infiltrating adenocarcinoma that arises from the epithelial cells of the pancreas. "In pancreatic ductal adenocarcinoma, tumor-mediated SIRT1 loss was accounted for the induction of NF-κB signaling in cachectic muscles." (PMID 36581870, 2022). "High SIRT1 expression has been associated with poorly differentiated pancreatic ductal carcinomas and poor disease outcomes." (PMID 34907162, 2021). "The aim of this study was to establish a protein expression profile for SIRT1-7 in pancreatic ductal adenocarcinomas (PDAC) and to determine if there were associations between SIRT1-7 expression, clinico-pathological parameters and patient outcome." (PMID 26121130, 2015). "This was further supported by the findings that SIRT1 inhibition can prevent acinar-to-ductal metaplasia and reduce pancreatic ductal adenocarcinoma (PDAC) tumours cell viability." (PMID 26121130, 2015). "Since data on the role of Sirt1 in pancreatic ductal adenocarcinoma (PDAC) are sparse, we investigated the expression profile and prognostic significance of Sirt1 in vivo as well as cellular effects of Sirt1 inhibition in vitro." (PMID 24088390, 2013). "However, investigating human tissue samples of fully developed pancreatic ductal adenocarcinoma, we only detected nuclear localized Sirt1." (PMID 24088390, 2013). "In pancreatic ductal adenocarcinoma, miR-217 inhibits tumor cell growth by targeting KRAS and SIRT1." (PMID 28437471, 2017).
pneumonia (7 papers, 2021 to 2025). An acute, acute and chronic, or chronic inflammation focally or diffusely affecting the lung parenchyma, caused by an infection in one or both of the lungs (by bacteria, viruses, fungi, or mycoplasma.). "Next, we investigated the effect of the small molecule SRT1720, a Sirt1 activator, in human monocytes, as well as in a mouse model of pneumonia." (PMID 41096578, 2025). "Recent findings suggest that pneumonia induces a functional knockdown of Sirt1 in the lungs of wild-type mice." (PMID 41096578, 2025). "The normalization of Sirt1 expression during the recovery phase in CAP patients suggests that Sirt1 may play a role in regulating the resolution of the inflammatory response following pneumonia." (PMID 41096578, 2025). "There is evidence that the PPARα/γ-adenosine 5′-monophosphate- (AMP-) activated protein kinase- (AMPK-) sirtuin-1 (SIRT1) pathway and fatty acid metabolism may be involved in influenza A virus (IAV) replication and pneumonia caused by IAV." (PMID 37325475, 2023). "However, there is little data on the regulation of Sirt1 in myeloid cells during pneumonia." (PMID 41096578, 2025). "Additionally, pneumonia has been shown to induce a functional knockdown of Sirt1 in the lungs of mice within four hours, leading to Sirt1 levels comparable to those observed in Sirt1-deficient mice, indicating that this effect is not limited to the systemic compartment." (PMID 41096578, 2025). "Furthermore, CA activates SIRT1 to inhibit nuclear translocation of HMGB1 and M2 polarization, thereby alleviating Klebsiella pneumoniae-induced pneumonia in AMs." (PMID 35873636, 2022). "The peroxisome proliferator-activated receptor (PPAR) α/γ-adenosine 5′-monophosphate- (AMP-) activated protein kinase- (AMPK-) sirtuin-1 (SIRT1) pathway and fatty acid metabolism are reported to be involved in influenza A virus (IAV) replication and IAV-pneumonia." (PMID 34540999, 2021).
prostatic intraepithelial neoplasia (7 papers, 2011 to 2025). "Notably, homozygous deletion of the SIRT1 gene in mice led to the development of prostatic intraepithelial neoplasia (PINs), associated with impaired autophagy." (PMID 39796040, 2024). "In Sirt1 knockout mice increased cell proliferation of prostatic intraepithelial neoplasia was observed, implicating Sirt1 as a tumor suppressor." (PMID 32426286, 2020). "Low SIRT1 expression promotes prostatic intraepithelial neoplasia development." (PMID 40941911, 2025). "SIRT1 limits prostatic intraepithelial neoplasia in SIRT1-knockout mice." (PMID 31956359, 2020). "H2AFZ and SIRT1 transcript levels were assessed in primary PCa, as well as in high-grade prostatic intraepithelial neoplasia (PIN) and morphologically normal prostate tissue (NPT)." (PMID 24127549, 2013).
retinoblastoma (7 papers, 2018 to 2025). A malignant tumor that originates in the nuclear layer of the retina. "Insulin like growth factor 2 mRNA binding protein 3 (IGF2BP3)-mediated N6-methyladenosine of USP49 enhances carboplatin resistance in retinoblastoma by promoting autophagy through stabilizing Sirtuin 1 (SIRT1)." (PMID 41035649, 2025). "Stress response proteins that were identified to be hyperphosphorylated in retinoblastoma compared to control retina tissues included H2AFX, SIRT1, TNIK, WRNIP1, BAZ1B, and CDK1." (PMID 29914080, 2018). "Regarding cancer progression its role is controversially discussed and is known to differ in respect to tissue and cancer entity: SIRT1 expression does not seem to have any prognostic significance in retinoblastoma." (PMID 32388637, 2020).